IL15 (interleukin 15)
Diseases named in the same sentence as IL15 in open-access papers (continued):
Sharing a sentence is not in itself a finding about the gene and the disease.
uveitis (5 papers, 2020 to 2025). An inflammatory process affecting a part of or the entire uvea. "Although TriKEs used in these studies contained IL-15, and IL-15 elicited severe toxicity (bowel ischemia, pneumonitis, papilledema, uveitis and grade 3 hypotension) and death in humans, IL-15-incorporting TriKEs showed no observable detrimental effects in mice." (PMID 33802954, 2021). "However, in a phase I clinical trial, patients with various solid tumors had eight serious adverse events (bowel ischemia, pneumonitis, papilledema, uveitis and grade 3 hypotension), and further studies are required to evaluate the safety and toxicity of IL-15 in humans." (PMID 33802954, 2021). "Our proof-of-concept study demonstrates that blocking IL-7 or IL-15 leads to specific depletion of the uveitogenic memory CD4+ T cells and disruption of disease chronicity in uveitis." (PMID 40323267, 2025). "We selected the chemokine/chemokine receptor genes IL10 receptor (IL10R), IL15, IL15 receptor α (IL15RA) and the adhesion gene ICAM1 that were believed to be the common biomarkers of many forms of uveitis." (PMID 36163311, 2022).
visceral leishmaniasis (5 papers, 2010 to 2024). A severe form of leishmaniasis characterized by irregular bouts of fever, substantial weight loss, swelling of the spleen and liver, and anemia (which may be serious). "In visceral leishmaniasis, it was shown that IL-15 is produced during the infection caused by Leishmania infantum and increases the killing of this parasite." (PMID 39844838, 2024). "In the present report we therefore addressed three questions using the mouse model of experimental visceral leishmaniasis: (i) Does IL-15 function as NK-cell-stimulatory cytokine as predicted from the results obtained in other systems?" (PMID 20213736, 2010). "In conclusion, our analysis of the early NK-cell effector response in visceral leishmaniasis revealed differential functions for the cytokines IL-12, IL-15 and IL-18." (PMID 20213736, 2010). "Patients coinfected with HIV and visceral leishmaniasis exhibited lower splenic CD4+ cell density and reduced expression of genes such as IL15." (PMID 38843306, 2024). "We conclude that IL-15 is not functioning as a universal NK-cell priming signal and that IL-18 contributes to the NK-cell response in visceral leishmaniasis." (PMID 20213736, 2010). "Our data clearly illustrate that the full induction of NK-cell effector functions in visceral leishmaniasis requires IL-12 and IL-18, but – unexpectedly – is entirely independent of IL-15." (PMID 20213736, 2010).
Anxiety (4 papers, 2021 to 2025). Intense feelings of nervousness, tension, or panic often arise in response to interpersonal stresses. "Notably, we propose that IL-15 may play a crucial role in mediating the relationship between air pollutants and depressive mood and anxiety." (PMID 40611827, 2025). "IL15 may modulate gamma-aminobutyric acid (GABA), a neurotransmitter inhibitory and serotonin transmission, ultimately disrupting anxiety, mood, sleep, and memory." (PMID 38178237, 2024).
bacteremia (4 papers, 2010 to 2023). "The presence of bacteremia was associated with low concentrations of HGF (p = 0.005), IL-15 (p = 0.002), IL-6 (p = 0.05), IP-10 (p = 0.008), MIG (p = 0.03) and MIP-1α (p = 0.03)." (PMID 28628613, 2017). "Consistently, in multi-marker analysis we found that the most relevant markers associated with presence of bacteremia were HGF, IL-15, IL-6, IP-10, MIG and MIP-1-α and additionally, G-CSF, IFN-γ, RANTES." (PMID 28628613, 2017). "Compared with controls, the levels of IL-6, IL-8, IL-9, IL-15, IL-17, IP-10 and TNFα were significantly elevated in the bacterial sepsis-ARDS group." (PMID 21062445, 2010). "In the bacterial sepsis-ARDS group, levels of IL-6, IL-8, IL-9, IL-15, IL-17, IP-10 and TNFα are also increased versus the control group." (PMID 21062445, 2010). "Subjects with detectable bacteremia had lower levels of HGF (p = 0.005), IL-15 (p = 0.002), IL-6 (p = 0.05), IP-10 (p = 0.008), MIG (p = 0.03) and MIP-1α (p = 0.03) compared to subjects without bacteremia." (PMID 28628613, 2017).
Burkitt lymphoma (4 papers, 2021 to 2024). A rare form of malignant mature B-cell non-Hodgkin lymphoma. "Studies have shown that the combination of anti-CD20 or anti-CD79 antibodies with NKTR-255 (a polymer-conjugated, IL-15Rα-dependent, recombinant human IL-15 agonist) can significantly enhance the in vitro cytotoxicity of CD19-CAR-NK cells against Burkitt’s lymphoma (BL) cells." (PMID 39007146, 2024). "To assess the capacity of NK cells from Hu-NSG-Tg(IL-15) to mediate ADCC, we co-cultured splenic NK cells from Hu-NSG-Tg(IL-15) and human donors with the Raji Burkitt lymphoma cell line." (PMID 36851579, 2023). "Another group used mRNA electroporation to engineer moDCs to produce IL-15/IL-15Rα or IFN-α leading to increased NK cell activation and cytotoxic activity against Burkitt lymphoma cells in vitro." (PMID 34054844, 2021).
diabetic nephropathy (4 papers, 2019 to 2026). "Our data show that different human chronic kidney diseases are characterized by a strong decreased expression of intrarenal IL-15, which is particularly relevant in diabetic nephropathy, in which type 2 tubular EMT plays an important role in fibrosis." (PMID 31360169, 2019). "Thus, it is tempting to speculate that IL-15 antifibrotic actions on tubular epithelial cells may be involved in CKD, such as diabetic nephropathy, in which the EMT process has been more clearly associated with renal fibrogenesis." (PMID 34769128, 2021). "Indeed, IL-15 protein expression is drastically decreased in chronic inflammatory nephropathies evolving toward fibrosis, such as acute interstitial nephritis (AIN), IgA nephropathies, and diabetic nephropathy." (PMID 34769128, 2021). "Indeed, immunohistochemistry analysis shows a high expression level of IL-15 in normal kidneys, mostly in tubular cells (n=5) while a significantly decreased IL-15 expression (p<0.01) was observed in acute interstitial nephritis (AIN) (n=5), IgA nephropathies (n=7), and diabetic nephropathy (n=6)." (PMID 31360169, 2019).
eosinophilic esophagitis (4 papers, 2014 to 2025). Eosinophilic esophagitis (EoE) is a chronic, allergic disease of the esophagus characterized clinically by symptoms of esophageal dysfunction (including vomiting, dysphagia, feeding disorders, food impaction and abdominal pain) which persist after treatment with proton pump inhibitors (PPIs). "It has been hypothesized in a model of human eosinophilic esophagitis that IL-15 could stimulate helper T cells to produce eosinophil-selective chemoattractants." (PMID 30837635, 2019). "In a preclinical study regarding RCeD and eosinophilic esophagitis (EoE), the authors reported that treatment with CALY-002 significantly reduced the IELs in IL-15TgE mice (a mouse model of IL-15 overexpression) and the natural killer (NK) cells in cynomolgus monkeys." (PMID 41010485, 2025).
Ewing sarcoma (4 papers, 2012 to 2025). A small round cell tumor that lacks morphologic, immunohistochemical, and electron microscopic evidence of neuroectodermal differentiation. "Pre-activation of natural killer cells by either recombinant human IL-15 or co-culture with genetically modified IL-15/4-1BBL expressing K562 feeder cells results in more efficient recognition and lysis of Ewing sarcoma cells." (PMID 22587892, 2012). "Activation of natural killer cells with IL-15 increased specific cytolysis of chemotherapy-resistant Ewing sarcoma to levels similar to those observed for chemotherapy-sensitive cells." (PMID 22587892, 2012). "Together, these data indicate that pre-activation of natural killer cells with IL-15 can overcome resistance of chemotherapy-resistant Ewing sarcoma to natural killer cell-mediated cytolysis." (PMID 22587892, 2012). "Importantly, the relative resistance of chemotherapy-resistant Ewing sarcoma cells to lysis by resting natural killer cells could be overcome by pre-activation of natural killer cells with IL-15." (PMID 22587892, 2012). "In Ewing sarcoma, there were 21 significant relationships, including IL-4/IL-1β (r2 = 0.55, p = 0.00048), IL-4/IL-8 (r2 = 0.68, p = 0.0000047), CXCL14/IL-15 (r2 = 0.61, p = 0.00013), and CXCL5/CXCL12 (r2 = 0.64, p = 0.000030)." (PMID 41008853, 2025).
lymphoid tumors (4 papers, 2020 to 2025). "Our results suggest that drugs blocking translation, IL-15, JAK or mTOR downstream of this cytokine might concur in the treatment of lymphoid tumors of NK cell origin depending on MYC." (PMID 37105715, 2023).
lymphoproliferative disorder (4 papers, 2020 to 2025). "A controversial issue regarding the use of IL15-based therapy for treating lymphoproliferative disorders is the pathogenic role of IL15 in these malignancies." (PMID 39858511, 2025).
myositis (4 papers, 2013 to 2020). "In myositis, a report based on patients with PM and DM showed an upregulation of IL-15 in muscle fibers and serum, in correlation with disease severity." (PMID 32775472, 2020). "The researchers' opinion was that IL-15, as a key regulator in PM, is likely to become a promising therapeutic target and a possible treatment for multiple myositis." (PMID 32775472, 2020). "IFN-α, another cytokine up-regulated in myositis muscle, induced Il15 and Il15ra mRNA and IL-15/IL-15Rα complex protein to the level similar to those induced by IFN-γ or TNF-α." (PMID 26417430, 2015). "Consistently, elevation of IL-15 protein has been observed in the skeletal muscle of myositis patients." (PMID 26417430, 2015). "Cultured human myoblasts from patients with myositis constitutively produce a low level of cytoplasmic and secreted IL-15, which was also observed in healthy controls; however, mRNA and protein production was increased in DM patients by stimulation with IL-1α, IL-1β, TNF-α, or IFN-γ." (PMID 30766892, 2019). "Together, these results indicate that the expression of the IL-15/IL-15Rα complex protein by skeletal muscle cells was undetectable under steady state conditions, while induced by TNF-α, IFN-γ, or IFN-α that associates with Th1 response in myositis." (PMID 26417430, 2015). "In myositis patients, IL-15 protein is up-regulated in the skeletal muscle." (PMID 26417430, 2015). "Given the supporting role of IL-15 in CD8+ T-cell survival and activation and the pathogenic role of cytotoxic CD8+ T cells in polymyositis and inclusion-body myositis, we hypothesize that IL-15 produced by the inflamed skeletal muscle promotes myositis via CD8+ T cells." (PMID 26417430, 2015). "Rather than being used by the muscle cell itself, the skeletal muscle IL-15 directly promotes the effector function of memory-like CD8+ T cells, which facilitates the formation of a pro-inflammatory skeletal muscle microenvironment during myositis progression." (PMID 26417430, 2015). "However, the exact role of IL-15 in myositis is not yet known enough, and further studies are needed to bring new data on this." (PMID 32775472, 2020). "However, the role of skeletal muscle IL-15 in myositis has not been reported." (PMID 26417430, 2015).
nephritis (4 papers, 2012 to 2021). Inflammation of renal tissue. "Based on the ability of IL-15 to counter inflammation by inhibiting the induction of MCP-1 in a nephritis mouse model, we assessed by RT-qPCR MCP-1 levels in a UUO model." (PMID 34769128, 2021). "Indeed, experiments in IL-15-/- and IL-15Rα-/- mice show that intrarenal IL-15, present both as secreted and membrane-bound, forms (mbIL-15) anchored through the IL-15Rα chain and protects kidney epithelial cells, counteracting apoptosis, and inflammation during nephritis." (PMID 31360169, 2019). "Thus, our results support the notion that the renoprotective effect of IL-15 observed in the UUO model could be related in part to its ability to counteract inflammation by inhibiting MCP-1 induction, as published in nephritis mouse models." (PMID 34769128, 2021).
polymyositis (4 papers, 2015 to 2021). A rare idiopathic inflammatory myopathy characterized by symmetric proximal muscle weakness and elevated muscle enzymes. "Muscle biopsy specimens acquired from polymyositis (PM) patients show an upregulation of MICA/B correlating with IL-15 expression by muscle cells and the identification of CD8+ NKG2D+ cells within inflammatory infiltrates." (PMID 35821998, 2021).
pulmonary TB (4 papers, 2021 to 2023). "Thus, further studies are warranted to elucidate the potential effect of IL-15 on the NK cell homeostasis in pulmonary TB patients with cavity." (PMID 34646890, 2021). "Our study identified unique gene signatures (IL-27, STAT1, IRF1, TLR4, IL-15, IL-2RA, IL-24, TGFβ, CD28, CD80, NFATC1, and PTGDR2) that discriminate active pulmonary TB from uninfected controls using unstimulated PBMCs." (PMID 37460564, 2023).
renal fibrosis (4 papers, 2018 to 2022). A final common manifestation of a wide variety of chronic kidney diseases characterized by glomerulosclerosis and tubulointerstitial fibrosis. "We found that M-MDSC supernatant attenuated the systemic inflammation associated with renal fibrosis via IL-15." (PMID 35252184, 2022). "By analyzing the published GSE83610 dataset, CD44 was shown to be inversely related to IL-15 expression in the rat renal medulla of lithium-induced renal fibrosis." (PMID 35252184, 2022). "Treatment with M-MDSC supernatant ameliorated renal fibrosis and myofibroblastic differentiation in RRMSCs through IL-15." (PMID 35252184, 2022). "In this study, we demonstrated the antifibrotic effect of IL-15 in an experimental model of renal fibrosis." (PMID 34769128, 2021). "Then, we decided to decipher the possible protective role of IL-15 in a model of renal fibrosis where the profibrotic cytokine TGF-β plays a prominent role, e.g., UUO in mice." (PMID 34769128, 2021). "We highlighted that IL-15 per se prevents renal fibrosis through a direct action on collagen synthesis on myofibroblasts as well as by reducing macrophage infiltration in UUO." (PMID 34769128, 2021). "Further experiments are needed to better understand the complexities of action of IL-15 on both innate lymphoid cells and renal cellular components (e.g., epithelial cells, fibroblasts), especially in renal fibrosis." (PMID 34769128, 2021). "In this manuscript, we have explored the intrarenal IL-15 expression in different human inflammatory nephropathies evolving towards renal fibrosis and observed an important decreased expression, as shown in murine models." (PMID 31360169, 2019). "Taken together, these data suggest that a decline in renal-derived IL-15 is detrimental to kidney function, favouring renal fibrosis development." (PMID 31360169, 2019). "Sirius red and Masson staining showed that M-MDSC supernatant downregulated IRI-induced renal fibrosis, which could be reversed by IL-15 mAb treatment." (PMID 35252184, 2022). "Treatment with M-MDSC supernatant ameliorated renal fibrosis and myofibroblastic differentiation in RRMSCs via IL-15, which may have implications in ameliorating renal fibrosis." (PMID 35252184, 2022). "In our study, M-MDSC supernatant and IL-15 regulated CD44 expression on the cell membrane of TGF-β1-induced MSCs, which suggested that M-MDSC supernatant and IL-15 may be involved in reducing the adhesion and migration of MSCs during renal fibrosis." (PMID 35252184, 2022). "We first investigated whether IL-15 expression is reduced in nephrectomized allografts from patients with Chronic Allograft Dysfunction and renal fibrosis." (PMID 34769128, 2021). "Therefore, IL-15 has the potential of blunting renal fibrosis, through direct roles in tubule protection and in collagen synthesis by myofibroblasts, but also, indirectly, through the modulation of inflammation." (PMID 34769128, 2021). "Taken together, our study highlights a major role of IL-15 on myofibroblasts and macrophages, two main effector cells in renal fibrosis, demonstrating that IL-15 may represent a new therapeutic option for CKD." (PMID 34769128, 2021). "In this context, intrarenal IL-15 could act on other events involved in the renal fibrosis, inhibiting for instance the induction of the nephritogenic chemokine, MCP-1, a powerful chemoattractant for macrophages that are a powerful source of TGF-β." (PMID 31360169, 2019). "However, whether IL-15 participates in regulating different MDSCs during renal fibrosis needs further study." (PMID 35252184, 2022). "Thus, acting on different actors of renal fibrosis, in particular tubular cells, it is tenting to speculate that the decreased IL-15 activity during kidney injury could be a crucial event in the fibrosis development." (PMID 31360169, 2019).
renal fibrosis (continued). "Indeed, we found that IL-15 level in renal mouse model was significantly increased compared with the TSF-treated mice, suggesting that increased expression of IL-15 may enhance proinflammatory actions leading to the renal fibrosis." (PMID 29682583, 2018). "The protective potential of IL-15 in renal fibrosis in vivo has not been evaluated." (PMID 34769128, 2021).
respiratory infections (4 papers, 2010 to 2018). "IL-15 has been shown to be dispensable for the development and maintenance of memory cells that develop from respiratory infections and CD122 is lost from CD8+ T cells within the respiratory tract." (PMID 25071780, 2014). "As previously noted, the development of TEM cells is dependent on IL-2 (and not IL-15) and IL-15 is also dispensable for CD8+ Tmem that develops following a respiratory infection, which generates substantial TRM compared to systemic infection." (PMID 25071780, 2014).
rhabdomyosarcoma (4 papers, 1998 to 2022). A rare aggressive malignant mesenchymal neoplasm arising from skeletal muscle. "In line with our results, other authors have previously demonstrated that stimulation with IL-15 enhanced the cytotoxicity of NK cells against K562 targets, primary acute leukemic blasts, and rhabdomyosarcoma cell lines." (PMID 29713323, 2018). "We recently reported that rhabdomyosarcoma cell lines express and secrete interleukin 15 (IL-15), a tightly regulated cytokine with IL-2-like activity." (PMID 9862562, 1998).
skin aging (4 papers, 2015 to 2023). The gradual irreversible changes in structure of skin that occur as a result of the passage of time.. "One study demonstrated the beneficial effects of endurance exercise on skin aging, revealing exercise-induced IL-15 as a novel regulator of mitochondrial function in aging skin." (PMID 37954446, 2023). "Exercising could also affect interleukin-15 levels, thus preventing skin aging." (PMID 36820091, 2021). "We hypothesize that fewer ‘pulses’ of IL-15 from skeletal muscle and other tissues during sedentary living are in part responsible for the accelerated degeneration of dermal fibroblasts that drive the clinical symptoms of skin aging." (PMID 25902870, 2015). "Thus, we elucidate a mechanism by which exercise confers health benefits to skin and suggest that low-dose IL-15 therapy may prove to be a beneficial strategy to attenuate skin aging." (PMID 25902870, 2015).